BEX2 (brain expressed X-linked 2)
Diseases named in the same sentence as BEX2 in open-access papers (continued):
Sharing a sentence is not in itself a finding about the gene and the disease.
hepatocellular carcinoma (4 papers, 2017 to 2023). A malignant tumor that arises from hepatocytes. "In hepatocellular carcinoma, BEX2 induces dormant cancer stem cell properties and results in poor prognostic of patients." (PMID 37777549, 2023). "BEX2 was highly expressed and required for maintaining dormant cancer stem cells in human cholangiocarcinoma and hepatocellular carcinoma (HCC)." (PMID 37777549, 2023).
prostate carcinoma (3 papers, 2016 to 2024). A carcinoma that arises from epithelial cells of the prostate gland. "The identification of potential biomarkers such as APRT, CCL2, BEX2, MGC26963, and PLAU through specific gene modules and key genes could enhance our perception of prostate cancer's molecular mechanisms and targeted treatments." (PMID 38970097, 2024).
leukemia (2 papers, 2018 to 2021). A malignant (clonal) hematologic disorder, involving hematopoietic stem cells and characterized by the presence of primitive or atypical myeloid or lymphoid cells in the bone marrow and the blood. "In cell lines of leukemia, BEX2 was found to be expressed in MLLmu AML." (PMID 34803456, 2021). "The following sections summarize the eight top-ranked genes in some of the major drug classes (FLT3, CASP8AP2, L2HGDH, MNT, BAZ2B, MZF1, BEX2, and SMARCA4) that are highly likely to have notable biological significance in leukemia." (PMID 29298978, 2018).
lung carcinoma (2 papers, 2020 to 2023). "Here, we report that crotonylated BEX2 plays an important role in inhibiting chemotherapeutic agent-induced apoptosis via enhancing mitophagy in human lung cancer cells." (PMID 37777549, 2023). "Moreover, BEX2 crotonylation at K59 is critical in the BEX2-mediated mitophagy in lung cancer cells." (PMID 37777549, 2023). "Our data suggest that targeting BEX2 might be an attractive therapeutic strategy for lung cancer treatment." (PMID 37777549, 2023). "Because the endogenous Parkin in most lung cancer cell lines is expressed minimally, we next evaluated the role of BEX2-regulated mitophagy in lung cancer cell lines without overexpression of Parkin." (PMID 37777549, 2023).
non-small cell lung carcinoma (2 papers, 2023 to 2025). A group of at least three distinct histological types of lung cancer, including non-small cell squamous cell carcinoma, adenocarcinoma, and large cell carcinoma. "A recent study revealed that crotonylated BEX2 interacts with NDP52 and enhances mitophagy to modulate the apoptosis induced by chemotherapeutic agents in non-small cell lung cancer cells." (PMID 41000388, 2025).
oligodendroglioma (2 papers, 2010 to 2021). A well-differentiated (WHO grade II), diffusely infiltrating neuroglial tumor, typically located in the cerebral hemispheres. "These authors have demonstrated that down-regulation of galactin 1 in oligodendroglioma cells results in a marked reduction of BEX2 expression." (PMID 20482821, 2010).
Alzheimer disease (1 paper, 2024). A progressive, neurodegenerative disease characterized by loss of function and death of nerve cells in several areas of the brain leading to loss of cognitive function such as memory and language. "Our study reveals common molecular pathways in Alzheimer's disease (AD) and atherosclerosis (AS), notably in genes like BEX2, NKRF, SOD1, UBL5, ZBTB17, and ZNHIT3." (PMID 38738952, 2024).
cholangiocarcinoma (1 paper, 2020). A carcinoma that arises from the intrahepatic biliary tree (intrahepatic cholangiocarcinoma) or from the junction, or adjacent to the junction, of the right and left hepatic ducts (hilar cholangiocarcinoma). "The analysis of the cell cycle phases after introduction or knockdown of BEX2 demonstrated that BEX2 is involved in the induction of the G0 phase in cholangiocarcinoma cells." (PMID 33299012, 2020). "Here, we screened differentially expressing genes in a CSC-enriched fraction in cholangiocarcinoma and identified BEX2 as a key molecule for maintaining dormant CSCs." (PMID 33299012, 2020). "We demonstrated that BEX2 plays critical roles in the maintenance of dormant cancer stem cells in cholangiocarcinoma." (PMID 33299012, 2020). "Similar to the RBE cell line, in the cholangiocarcinoma cell line HuCCT1, BEX2 or CD274 expression was mutually exclusive." (PMID 33299012, 2020). "Here we found that BEX2 was highly expressed in CD274low cells, and that BEX2 knockdown decreased the tumorigenicity and G0 phase of cholangiocarcinoma cells." (PMID 33299012, 2020). "In conclusions, we demonstrated that BEX2 is essential for maintaining dormant cancer stem cells through the suppression of mitochondrial activity in cholangiocarcinoma." (PMID 33299012, 2020). "In cholangiocarcinoma cells, we found that BEX2 was degraded within 3 h through its interaction with the FEM1B-CUL2 E3 ubiquitin ligase complex." (PMID 33299012, 2020). "As HuCCT1 cells could proliferate but cannot develop heterogenous tissue in mice, we stained newly established cholangiocarcinoma-xenografted samples (CHOL4) with anti-BEX2 and anti-Ki67 antibody and got similar results." (PMID 33299012, 2020). "Thus, BEX2 is produced in cholangiocarcinoma cells and plays a critical role in dormant cancer stem cells." (PMID 33299012, 2020). "Therefore, we hypothesize that agonistic compounds of the FEM1B-CUL2 E3 ubiquitin ligase complex could be suitable therapeutic tools that degrade BEX2 proteins in cholangiocarcinoma stem cells." (PMID 33299012, 2020). "We analyzed differential gene expression in CD274-knockdown and control cells and identified BEX2, whose expression is mutually exclusive to CD274 expression in a variety of cancer cells, including cholangiocarcinoma cells." (PMID 33299012, 2020).
endometrial adenocarcinoma (1 paper, 2013). "The biologically-prioritized candidate gene, BEX2, is associated with estrogen, cell cycle, and apoptosis pathways and over-expressed in Ishikawa cells, a well-differentiated human endometrial adenocarcinoma cells, treated with BPA." (PMID 23590724, 2013).
Hepatic fibrosis (1 paper, 2024). The presence of excessive fibrous connective tissue in the liver. "The upregulated pathways in UHRF1-null adipocytes included those linked with pulmonary fibrosis, hepatic fibrosis, ID1 signaling, pulmonary healing pathway, signaling by Rho Family GTPase, and Bex2 signaling." (PMID 38789534, 2024).
Hyperglycemia (1 paper, 2024). An increased concentration of glucose in the blood. "BEX2 is known for regulating cell survival and apoptosis, potentially protecting retinal neurons from hyperglycemia-induced damage in DR." (PMID 39697326, 2024).
intrahepatic cholangiocarcinoma (1 paper, 2020). A carcinoma that arises from the intrahepatic bile duct epithelium in any site of the intrahepatic biliary tree. "Our findings present BEX2-related mitochondrial pathway as a potential therapeutic target for intrahepatic cholangiocarcinoma." (PMID 33299012, 2020).
leukoplakia (1 paper, 2016). A white patch or plaque on a mucous membrane that cannot be characterized clinically or pathologically as any other disease. "The correlation of low BEX4 expression with poor cancer-free survival in leukoplakia patients was more significant than other BEX family members including BEX1, BEX2, NGFRAP1 (BEX3) and BEX5." (PMID 27297407, 2016).
liver cancer (1 paper, 2022). An epithelial or non-epithelial malignant neoplasm that arises from the liver. "Brain ‐expressed X‐linked gene 2(BEX2) has been found to repair dormant cancer stem cells in liver cancer, and has shown cancer-promoting activity in several cancers." (PMID 36468004, 2022).
lung adenocarcinoma (1 paper, 2023). A carcinoma that arises from the lung and is characterized by the presence of malignant glandular epithelial cells. "Taken together, these results demonstrate that BEX2 is overexpressed in lung adenocarcinoma and is associated with poor prognosis in lymph node metastasis-free patients and clinical stage (I + II) patients." (PMID 37777549, 2023). "We also confirm that BEX2 is overexpressed in lung adenocarcinoma and is associated with poor prognosis in lymph node metastasis-free cancer." (PMID 37777549, 2023). "In lymph node metastasis-free lung adenocarcinoma, high expression of cytoplasmic BEX2 correlated with lower survival, and the same result was obtained in stage (I + II)." (PMID 37777549, 2023).
lymph node metastasis (1 paper, 2023). "Moreover, high expression of cytoplasmic BEX2 correlated with lower survival in lymph node metastasis-free cases." (PMID 37777549, 2023).
metastatic colorectal cancer (1 paper, 2020). "BEX2 has been reported to be involved in tumor development in several types of cancer, but its role in metastatic colorectal cancer remains largely undefined." (PMID 31929751, 2020).
myeloma (1 paper, 2022). "This was consistent with our IPA analysis results in myeloma showing BEX2 signaling as the top canonical pathway associated with CLF treatment." (PMID 35646666, 2022).
neuroblastoma (1 paper, 2017). Neuroblastoma (NB) is the most common solid, extracranial childhood tumor. "Our results from curcumin treated N2a neuroblastoma cells indicated the induction of Bex1, Bex2 and Bex3 genes prior to activation of apoptotic pathways and continued to last for 24 hours post treatment." (PMID 28145533, 2017).
ovarian carcinoma (1 paper, 2021). A malignant neoplasm originating from the surface ovarian epithelium. "Seven pathways such as VEGF family ligand-receptor interactions, nitric oxide signaling in the cardiovascular system, VEGF signaling, eNOS signaling, white adipose tissue browning pathway, ovarian cancer signaling, and BEX2 signaling pathway were enriched in kidney Treg (E-MTAB-7961)." (PMID 34084175, 2021).
schizophrenia (1 paper, 2024). A major psychotic disorder characterized by abnormalities in the perception or expression of reality. "Within the CGE, genes with high expression specificity for two calretinin (CALB2)-positive sub-populations of developing GABAergic neurons were also enriched for schizophrenia genetic liability (CGE-N-1, marker: NRIP3, and CGE-N-2, markers: BEX2, ARL6IP5, VSTM2A)." (PMID 38869145, 2024).
Stroke (1 paper, 2024). Sudden impairment of blood flow to a part of the brain due to occlusion or rupture of an artery to the brain. "TLR5 and P4HA1 are positively associated with glycolysis in both diseases; while BEX2 is negatively associated with glycolysis in both stroke and MS." (PMID 39021802, 2024). "First, we found several metabolic pathways shared in two diseases and BEX2 is negatively associated with glycolysis in both stroke and MS, while TLR5 and P4HA1 are positively associated with glycolysis in stroke and MS." (PMID 39021802, 2024).
viral infections (1 paper, 2023). "Given that this gene is down-regulated in a variety of viral infections, it may be that Bex2 is a protective gene that is targeted for inhibition by the invading virus." (PMID 38107402, 2023).
tumor (23 papers, 2010 to 2025). "Interesting findings include that SOX2 regulates the expression of SOX family proteins SOX1 and SOX18, and that SOX2 down regulates BEX1 (brain expressed X-linked 1) and BEX2 (brain expressed X-linked 2), two genes with tumor suppressor activity in GBM." (PMID 21211035, 2011). "In addition, the K59R mutation of BEX2 sensitizes tumor cells to apoptosis." (PMID 37777549, 2023). "Conversely, inhibition of BEX2-regulated mitochondrial autophagy increased the sensitivity of tumor cells to apoptosis." (PMID 39513918, 2024). "BEX2 was identified as upregulated in HBV tumor tissue (logFC = 1.3, p = 0.0026) and down-regulated in HCV tumor tissue (logFC = −1.9, p = 7.6×10−11)." (PMID 39005337, 2024). "We demonstrated that inhibition of BEX2-regulated mitophagy sensitized tumor cells to apoptosis, suggesting that mitophagy plays a protective and pro-survival role in these cells." (PMID 37777549, 2023). "Recently, BEX2 was found to be localized in cytosol and/or mitochondria and regulate apoptosis in cancer cells and tumor growth." (PMID 37777549, 2023). "Following treatment with doxorubicin and liensinine, the tumor weight and tumor growth rate were measured to evaluate the role of BEX2-mediated mitophagy in doxorubicin resistance." (PMID 37777549, 2023). "We found that liensinine treatment alone inhibited BEX2-induced tumor growth, as evidenced by the reduced weight and growth rate of tumors." (PMID 37777549, 2023). "While in adjacent normal tissue, 12 (15.2%) of the 79 specimens showed high expression, indicating that there were more tumor tissues with high expression of cytoplasmic BEX2 than adjacent normal tissues." (PMID 37777549, 2023). "Regarding the mechanism of the tumor-promoting role of BEX2, we showed that BEX2 promoted tumor growth and inhibited doxorubicin-induced apoptosis in vivo, which was reversed by inhibiting mitophagy with liensinine." (PMID 37777549, 2023). "A large number of studies have reported that BEX2 increases migratory activity and inhibits the apoptosis of tumor cells by activating JNK and NF-κB signaling." (PMID 34576008, 2021). "We demonstrated by in vitro and in a xenograft mouse model that BEX1 or BEX2 possess tumor suppressor activity." (PMID 21211035, 2011). "We have previously shown that BEX1 and BEX2 are silenced in GBM tumor specimens and exhibited extensive promoter hypermethylation." (PMID 21211035, 2011). "Recently, it was shown that crotonylation of brain-expressed X-linked gene family (BEX2) at K59 promotes the interaction between NDP52 and LC3B, enhances mitochondrial autophagy, and promotes tumor growth in human lung cancer cells while also inhibiting chemotherapy-induced apoptosis." (PMID 39513918, 2024). "Moreover, the BEX2 + DOX+Lien group further inhibited tumor growth compared to the BEX2 + DOX group." (PMID 37777549, 2023). "Next, we decided to explore the role of BEX2 in tumor growth." (PMID 37777549, 2023). "In tumor tissue, 53 (66.3%) of the 80 specimens showed high expression of cytoplasmic BEX2." (PMID 37777549, 2023). "We further assessed the relationship between the expression level of BEX2 and tumor size (>5 cm)." (PMID 37777549, 2023). "Overall, we confirmed that BEX2 inhibits apoptosis and promotes tumor growth." (PMID 37777549, 2023). "The results showed that depletion of BEX2 strikingly inhibited tumor growth." (PMID 37777549, 2023). "Recent studies have revealed that BEX2 may localize in cytoplasm and/or mitochondria and regulate apoptosis and tumor growth in cancer cells." (PMID 37777549, 2023). "Afterwards, we assessed the effects of BEX2 on tumor metastasis in vivo by using mouse models." (PMID 31929751, 2020). "A single gene, BEX2 may not have a determinant role such that it can completely inhibit metastasis, while BEX2 may have certain regulatory effect on tumor masses in patients with Dukes D stage, especially in relation to hedgehog signaling molecules." (PMID 31929751, 2020).
tumor (continued). "Our data suggested that SOX2 might down regulate BEX1 and BEX2 expression, reducing their tumor suppressor activities and thus promoting carcinogenesis." (PMID 21211035, 2011). "Furthermore, BEX2 promotes tumor growth and inhibits apoptosis by regulating mitophagy in vivo." (PMID 37777549, 2023). "In addition, inhibition of BEX2-regulated mitophagy sensitizes tumor cells to apoptosis." (PMID 37777549, 2023). "Some researchers found that BEX2 was silenced in all tumor specimens and exhibited extensive promoter hypermethylation, and viral-mediated re-expression of BEX2 led to increased sensitivity to chemotherapy-induced apoptosis and potent tumor suppressor effects in vitro and in a xenograft mouse model." (PMID 33193579, 2020). "It downregulated several potential oncogenes (e.g., AEBP1, MIAT) and genes linked to GBM proliferation and migration (e.g., SOCS2, HCP5) while modulating Wnt signaling and up-regulating tumor suppressor genes (e.g., SPRY4, BEX2)." (PMID 39874307, 2025). "Depletion of BEX2 significantly retarded the tumorigenicity of MHCC97H cells, as indicated by tumor initiation, survival, and tumor volume." (PMID 29029472, 2017). "Moreover, the results also confirmed that the knockout of some genes, such as BEX2, significantly decreased the survival and proliferation rates and induced death in HNSCC tumor cells." (PMID 37568192, 2023). "Despite their contributions to tumor progression, the expression of three genes was not shown to be differentially expressed with radiotherapy (1.049-fold in BEX2, 1.057-fold in BEX3, and 1.064-fold in BEX5) in the microarray results." (PMID 34576008, 2021). "In addition, immunoblot analysis showed that reduction of BEX2 led to decreased expression of OPN and cyclin D1, and an increase in the level of cleaved-caspase 3 in tumor tissues derived from MHCC97H cells." (PMID 29029472, 2017).